IL1B (interleukin 1 beta)
Diseases named in the same sentence as IL1B in open-access papers (continued):
Sharing a sentence is not in itself a finding about the gene and the disease.
infection (continued). "To further confirm LM mainly activates NLRP3 inflammasome, we used wild-type and NLRP3−/− B6 cells to analyze the IL-1β release and caspase-1 activation upon LM infection (ATP and poly (dA:dT) were used as the NLRP3 and AIM2 inflammasome activators, respectively)." (PMID 26911557, 2016). "In addition, reduced caspase 1 and IL1-β levels were noted in cells and tissue infected with strains having a colonizing phenotype, while both were strongly induced following infection with the cytotoxic strains." (PMID 27511873, 2016). "Prior to this study, the role of inflammsome activating proteins important for IL-1β/IL-18 responses in mice following infection with Ft strains other than Fn was essentially unknown." (PMID 27926940, 2016). "IL-1β participates in the generation of systemic and local responses to infection and injury by generating fever, activating lymphocytes and by promoting leukocyte infiltration at sites of infection or injury." (PMID 27321752, 2016). "Axl-/- mice that were given IL-1β were completely protected and survived the infection." (PMID 27350258, 2016). "Interestingly, while JMJD3 was found to negatively regulate few of the mycobacteria-responsive M1 markers of macrophages viz., Il12, Il1b and Cxcl2, the expression of M2 markers like Arg1, Mrc1, Il10, Tgfb, Ccl17 and Ccl2 on infection were JMJD3-dependent." (PMID 27532872, 2016). "Infections with Staphylococcus species induced the highest expression of IL-1β." (PMID 27688601, 2016). "In addition, a recent study has shown that these neutrophils are able to sustain IL-1β production during acute ST infection due to their unique resistance to pyroptotic cell death on NLRC4 inflammasome activation." (PMID 27363812, 2016). "Aldwell and the coworkers, by contrast, observed enhanced expression of genes for the proinflammatory cytokines IL-1β, IL-6, and TNFα only after in vitro infection of bovine macrophages in bronchoalveolar fluid with pathogenic M. bovis, but not with attenuated BCG-mycobacteria." (PMID 27066505, 2016). "We found that DOX provoked generation of TNF-α and subsequently caused the activation of NF-κB and iNOS and increased the expression of genes required to control infection and injury, such as IL-1β and IL-6, indicating severe inflammatory conditions in the brain." (PMID 27120616, 2016). "Furthermore, analysis of tissue model supernatants revealed increasing IL-1β levels over the infection period, whereas in unstimulated models only background levels were detected." (PMID 27399650, 2016). "Indeed, NLRP3 was significantly increased in murine and human CF cells and its inhibition ameliorated inflammatory pathology in murine experimental infections and attenuated IL-1β production in human CF cells." (PMID 26972847, 2016). "Infection with WT K. pneumoniae induced significantly more IL-6 and CXCL2 than infection with the entB ybtS mutant, consistent with the siderophore-dependent effects observed and more IL-1β, which may be attributable to higher bacterial density." (PMID 27624128, 2016). "It is currently unknown whether the MAC triggers NLRP3 and IL-1β activation to defend against infection in liver recipients." (PMID 27063552, 2016). "Collectively, these findings suggest that, in gingiva, the upregulation of MMP12 may be a molecular hallmark of natural aging, while the upregulations of MMP3, MMM9, and IL1B may indicate externally (e.g., infection)-induced aging." (PMID 27391467, 2016). "IL-1β was rarely detected in PBMC infected with M. mass at low multiplicity of infection (MOI)." (PMID 27489303, 2016). "In addition to its direct impact on target cells, IL-1β stimulation augments chemokine production in cells at infection sites." (PMID 27231948, 2016). "Moreover, the MMP3, MMP9 and IL1B levels were more highly stimulated by infection with the oral bacterium, Fusobacterium nucleatum, in old hGFs compared to young hGFs." (PMID 27391467, 2016).
infection (continued). "IL-12, TNF-α, and IL-1β are proinflammatory cytokines, which are essential for resistance against infection, but when produced at high levels they may contribute to immunopathology." (PMID 27549173, 2016). "Moreover, we here show that the observed reduction of IL-1β maturation after infection takes place in both a murine and a human infection model." (PMID 26114647, 2015). "In this study, we show that IL-1β/IL-18 cytokine activation occurs early after bacteria enter the lung, and this activation eventually contributes to pulmonary inflammation and pathology during the later stages of infection." (PMID 25781467, 2015). "Moreover, the production of IL-1β was significantly elevated by D39-infection, whereas 3-MA treatment further increased IL-1β release from S. pneumoniae D39-infected BV-2 cells." (PMID 26683708, 2015). "Production of IL-1β would be the result of NFκB activation during infection." (PMID 26659062, 2015). "Given that the intestinal MP1 subset from infected mice produces significant amounts of IL-1β, C. rodentium may be capable of activating an inflammasome during infection." (PMID 26269452, 2015). "A key factor for inflammatory processes, also during infections, is IL-1β." (PMID 26114647, 2015). "Finally, we demonstrate that this IL-21-STAT3-dependent IL-1β expression can at least in part explain the pathologic immune response mediated by IL-21 during infection with Pneumonia Virus of Mice (PVM), a mouse model for human respiratory syncytial virus." (PMID 26269257, 2015). "The relative expression of IL-1β was induced following 6 h infection with both Ms_Rv1169c and Ms_Vec strains and their expression was decreased quickly at later time points, while the secretion of IL-1β was increased after 6 h infection in both bacterial infected macrophages." (PMID 26157429, 2015). "Conversely to what has been shown for E75CV1 the progression of the E75-infection resulted in a dramatic imbalance of the immune system by day 7 pi, with the significant up-regulation of 9 genes, namely: IL-5, IL-1β, IL-6, IL-8, IL-10,IL-21, IL-23, DEFB2 and TLR-3." (PMID 26589145, 2015). "Caspase-1−/− and IL-1β−/−IL-18−/− mice often exhibit similar infection response phenotypes." (PMID 26500655, 2015). "Elevated interferon gamma (IFNγ) and IL-1β also indicated infection-enhanced inflammation." (PMID 26619277, 2015). "At times early following infection, multiple transcripts encoding proinflammatory molecules were increased, including IL8 (8196-fold), IL1B (1559-fold), oncostatin M (OSM, 799-fold), CCR1 (588-fold), CXCR1 (625-fold), CXCR2 (596-fold), CCL4 (514-fold), and CCL3 (658-fold)." (PMID 25719526, 2015). "However, the limitation of IL-1β secretion in these p47phox-/- mice only slightly affected liver Bgp1 expression, and therefore live virus titers were still high at 72h of infection." (PMID 26367131, 2015). "However, in the late phase of infection, IL-1β secretion and caspase-1-dependent cell death were induced by ROS." (PMID 26683708, 2015). "This could be due to the secretion of neurotoxic molecules following infection, such as IL-1β and TNF-α." (PMID 25611061, 2015). "In this study, we provide evidence that CCR2+ monocytes are recruited to the intestinal lamina propria (LP) upon pathogen infection and rapidly give rise to a subset of intestinal MPs in situ that activate RORγt+ ILC3s through caspase-11 inflammasome-dependent IL-1β production." (PMID 26269452, 2015). "Thus far, the impairment of IL-1β after infection was attributed to a suppression of PKC-dependent signaling and the loss of ROS production." (PMID 26114647, 2015). "MGAS315 infection sites had higher IL-1β than MGAS6180 sites at 8 h after inoculation but decreased at 12 h whereas levels of IL-1β at MGAS6180 sites were higher at 12 h than at 8 h, suggesting that MGAS315 may have a mechanism to reduce IL-1β responses." (PMID 26047469, 2015).
infection (continued). "The dramatic increase found in sera of almost all the immune mediators tested: TNF-α, IFN-α, IL-12, IL-1β and sCD163 confirm the soluble factor storm suffered by acutely infected pigs in the latter phases of infection, most probably reflecting the massive tissue destruction found." (PMID 26589145, 2015). "Notably, pre-infection with C. burnetii induced a significantly higher expression of pro-casp-1 and pro-IL-1β, than single infections with L. pneumophila, possibly because of the presence of C. burnetii PAMPs during the 24-h pre-stimulation." (PMID 26687278, 2015). "IL-1β mediates part of the inflammatory response to both infection and injury." (PMID 25887955, 2015). "In addition, the expression of IL-1β, IL-18 and caspase-1 p10 was gradually increased and remained elevated until 7 h of infection." (PMID 26683708, 2015). "Specifically, TNF-α, GM-CSF, MIP-1α, IL-1α, IL-1β, IL-2, IL-3, IL-12p40, IL-12p70, and IL-17 levels were significantly reduced in UV-12 animals compared to vehicle control treated mice at both the 72 and 96 h post infection time points." (PMID 25984714, 2015). "Our findings suggest that the blockage of IL-1β might be an effective treatment for dopaminergic neuronal injury induced by early infection/inflammation." (PMID 25898410, 2015). "THP-1 cells or monocyte-derived Mø produce IL-1β and IL-18 after infection with HCV." (PMID 26549942, 2015). "Furthermore, it suggests the possibility that infection and sustained production of inflammatory cytokines, including IL-1β, IL-18, and IL-17, through lipid peroxidation results in chronic inflammation." (PMID 26783845, 2015). "In contrast, in the natural infection setting “free LPS” may be present in much lower amount and, under these circumstances, the adjuvant effect of IL-1β becomes essential for efficient expansion of B1a B cells." (PMID 25768794, 2015). "Overall, the two responses do not temporally overlap, as EMCV rapidly activates the signaling cascade required for iNOS, COX-2 and IL-1β expression within minutes of infection, while EMCV RNA accumulation is a slow process first detectable 4–6 hours post infection in macrophages." (PMID 26295266, 2015). "Infection with H. pylori significantly upregulated gastric expression of pro-inflammatory cytokines including: interferon gamma (IFNγ) (p<0.0001)., tumor necrosis factor alpha (TNFα), (p<0.0001) and Interleukin 1 beta (IL1β) (p<0.05)." (PMID 26575645, 2015). "Furthermore, selected analysis of T. rubrum and M. gypseum mycelial plug infections demonstrated IL-8 and IL-1β production, with both cytokines being secreted in larger amounts following M. gypseum infection (data not shown)." (PMID 25667269, 2015). "Rather, the eventual death of Il-1r1-/- mice may be due to failure of immune responses that are dependent on the presence of IL-1β in the early phase of infection but are effectively deployed only in the second week of infection." (PMID 25768794, 2015). "Correspondingly, cDCs from Il21r−/− mice had lower expression of pro-IL-1β after PVM infection." (PMID 26269257, 2015). "Whilst the present study provides several lines of evidence for the role of IL-1α in endometrial cell responses to infection followed by cell damage, we cannot exclude the possibility that IL-1β may also be involved." (PMID 25395028, 2014). "Infections of mBMDMs with ΔripA results in increased IL-1β secretion compared to wild-type." (PMID 24505427, 2014). "Infection of BMDMs and primary lung fibroblasts with C. trachomatis strain L2, or the murine pathogen C. muridarum, led to higher levels of MIP2 mRNA expression or IL-1β secretion from TRAIL-R-deficient cells than WT cells." (PMID 24695582, 2014). "Except for day 7 post-inoculation in the IL-1β deficient mice, no significant defects were observed between mouse strains in the proportion of neutrophils during infection." (PMID 25198773, 2014).
infection (continued). "Despite this significant limitation, the results reported here support the direct infection of at least a sub-set of white blood cells, and suggest that further investigation of inflammasome activation and the presence of IL-1β and IL-18 in CHIKF patients is warranted." (PMID 24721947, 2014). "Infection of monocytes and monocyte-derived DCs with chlamydial serovars Ba, D and L2 could induce detectable secretion of cytokines IL-8, IL-6, IL-1β, IL-10 and TNF." (PMID 25123797, 2014). "Interestingly, a very strong overexpression of IL-1β was observed after infection with the GD and VN NS-reassortants, detectable even in the absence of any in vitro re-stimulation." (PMID 24460592, 2014). "Furthermore, cytokine secretion (IL-1β, IL-6, IL-8) appears to be maintained for an extended period of infection." (PMID 25540075, 2014). "The aims of this study were to determine the effect of silibinin on pro-inflammatory mediators in (i) human fetal membranes and myometrium treated with bacterial endotoxin lipopolysaccharide (LPS) or the pro-inflammatory cytokine IL-1β, and (ii) in preterm fetal membranes with active infection." (PMID 24647589, 2014). "Impaired IL-1β induction may delay early antiviral responses and contribute to cellular accumulation late in infection." (PMID 24558422, 2014). "Collectively these roles facilitate IL-1β-stimulated extravasation of neutrophils and might thus be involved in supporting an efficient innate immune response to infection and injury." (PMID 24317296, 2014). "Moreover, il1b expression was found to be significantly higher in MO-c3.7/8s microinjected larvae than on WT 3 h after its stimulation with A. hydrophila bath infection." (PMID 24926798, 2014). "However, at day 3 post-infection, the Socs4R108X/R108X mice showed significantly higher levels of cytokines and chemokines, such as IL-1β, IL-4, IL-5, IL-6, IL-12p40, IL-13, IFN-γ, and KC (CXCL1), MIP-2 (CXCL2) and MCP-1 (CCL2), respectively." (PMID 24809749, 2014). "Despite these potential pitfalls, our individual infection controls for IL-1β secretion, phagosomal escape, and intracellular proliferation resulting from infection with bead-bound bacteria are consistent with previously published data based on infection by free bacterial cells." (PMID 24505427, 2014). "Furthermore, the HXB1 (NLRP1variant 5), HXB15 and HXB29 (NLRP1variant 1) RI strains also produced IL-1β after infection in a manner correlated with NLRP1 sequence and macrophage sensitivity to Toxoplasma." (PMID 24626226, 2014). "Furthermore, cytokine secretion (IL-1β, IL-6, IL-8) appears to be maintained for an extended period of infection, suggesting that a more chronic or persistent infection can maintain the pro-inflammatory condition." (PMID 25540075, 2014). "In particular, the produced IL-1b and IL-18 mediate repair responses such as angiogenesis and, via upregulation of cytokines and chemokines, induce the recruitment of inflammatory cells to the site of infection." (PMID 24667138, 2014). "The combination of IFNβ and IL1β showed the largest reduction of infection." (PMID 24616721, 2014). "The induction of GFP upon infection correlated with the upregulation of il1b mRNA." (PMID 24973754, 2014). "Regarding the release of IL-1β from microglia in response to HIV-1 or FIV infections and its relationship to pathogenesis, the multivariate analyses of FIV-infected animals suggested that elevated expression of caspase-1, NLRP3 and IL-1β contributed to the development of brain disease." (PMID 24886384, 2014). "To determine if C/EBPβ and PU.1 are produced in a manner that is consistent with the proposed role in IL-1β regulation, we quantified the expression of all three genes in the monocyte-like U937 cells after stimulation with heat killed Mtb or infection with the live attenuated strain of Mtb, H37Ra." (PMID 25329476, 2014).
infection (continued). "While similar levels of TNF-α and IL-6 were released after infection with low dose C. pneumoniae or stimulation with 1 ng/mL LPS, low dose C. pneumoniae induced higher levels of IL-1β, IL-12p40 and IL-12p70 over time than LPS, which was shown to be statistically significant." (PMID 25488836, 2014). "Consistently, adherent monocytes in our study failed to release significant amounts of IL-1β upon stimulation with LPS alone, whereas infection with C. pneumoniae, which provides both an extracellular and an intracellular stimulus, resulted in strong induction of IL-1β." (PMID 25488836, 2014). "In contrast, other authors hypothesized that a reduction in levels of IL-1β could attenuate the host's ability to fight an infection." (PMID 25299619, 2014). "A study in seabream leukocytes has revealed that infection of macrophage leads to caspase-1 independent processing and release of IL-1β as well as caspase-1 dependent pyroptotic cell death, suggesting a role for inflammasome and caspase-1 in the clearance of infected immune cells in teleost fish." (PMID 25306446, 2014). "Our data show that IL-1β is significantly up-regulated at all times through 120 hours post-infection of monocytes and thus is consistent with the cytokine profile in AD, suggesting that infection can be an initiating stimulus for this cytokine." (PMID 25540075, 2014). "Additionally we have shown that laticifer peptidases of C. procera promote downregulation of IL-1β, among other inflammatory mediators, during infection by S. Typhimurium." (PMID 24757289, 2014). "Infection elicited expression of the proinflammatory chemokines CXCLi1 (chemokine [C-X-C] motif) ligand i1), CXCLi2, and interleukin-1β (IL-1β) in the ceca of all breeds at 2 days postinfection (dpi)." (PMID 24987092, 2014). "Therefore, we measured IL-1β production in human CF macrophages after autophagy stimulation as a primary source of excess inflammatory cytokine production during infection." (PMID 24798083, 2014). "Wild-type bacteria fully complemented suppression of IL-1β secretion during mixed infections of wild-type and ΔpdpC (p = 0.77) but there was a slight increase in the wild-type and ΔripA mixed infection when compared to wild-type infections alone (p = 0.01)." (PMID 24505427, 2014). "Inflammation is a natural bodily response to damage or infection that is generally mediated by proinflammatory cytokines such as interleukin 1 beta (IL-1β), interleukin 6 (IL-6), and tumour necrosis factor alpha (TNFα), in addition to lipidic mediators such as prostaglandins and leukotrienes." (PMID 24772353, 2014). "The over expression of IL-1β found after the infection with the NS-reassortants might obey an increase of the virus replication in monocyte-like cells and macrophage-like cells, rather than a direct effect of the different NS-segments." (PMID 24460592, 2014). "Mice immunized with IB010 had significantly lower post-infection tissue bacterial loads and significantly lower serum levels of the pro-inflammatory cytokines IL-1β, TNF-α and IL-6 compared to control mice in a mouse model of disseminated A. baumannii infection." (PMID 25485716, 2014). "Interestingly, when we conducted infections in Nlrp3 KO BMDCs, we found minimal reduction in IL-1β levels compared to WT BMDCs; our observations suggests that C. difficile has the capacity to engage other, as yet unidentified NLRs during BMDC activation." (PMID 23922820, 2013). "The secretion of IL-1β leads to further production of pro-IL-1β through the IL-1 receptor as well as cascading to a pro-inflammatory immune response with an influx of inflammatory cells to the site of infection." (PMID 24312491, 2013). "To determine what cytokines might be promoting the increased IL-17 responses in IL10SD mice, we looked at gene expression of IL-6, IL-23, TGFβ1 and IL-1β 1 week after infection of control and IL10SD mice." (PMID 23555256, 2013).